VIM (vimentin)
Diseases named in the same sentence as VIM in open-access papers (continued):
Sharing a sentence is not in itself a finding about the gene and the disease.
tumor (continued). "The immunoprofile of the tumor was CD99 (+), calretinin (+), inhibin (+), alpha smooth muscle actin (+), vimentin (+), ER (−), PR (−), keratin AE1/AE3 (−), alpha fetoprotein (−), CD117 (−), and placental alkaline phosphatase (−)." (PMID 23762714, 2013). "The negative activity of CK AE1/AE3, EMA, CD10, CK7, and CD34 and positive activity of HMB-45, Vimentin, and SMA of the tumour were consistent with epithelioid angiomyolipoma." (PMID 24490095, 2013). "The AKT inhibitor, GSK690693, inhibited AKT, blocked the expression of ZEB1 and vimentin and restored the expression of E-cadherin following IR, thus preventing the migration and EMT of the tumor cells." (PMID 24179501, 2013). "Tumor sections from AMA-treated mice demonstrated a decreased expression of β-catenin, NF-κB/p65, and Vimentin, and an increased expression of E-cadherin, compared to samples from the control mice." (PMID 23840269, 2013). "Vimentin is both an EMT and EndoMT marker and is also over-expressed in tumor samples compared to normal tissues." (PMID 23785295, 2013). "The gain of mesenchymal cell markers such as Vimentin (VIM), Snail homolog 2 (SNAI2), and fibronectin (FN) has been observed in tumor progression." (PMID 23717581, 2013). "The tumour cells express desmin, neuron specific enolase (NSE), EMA, and vimentin and show a high proliferative activity." (PMID 23406299, 2013). "Immunohistochemically, the tumour cells showed positive staining for epithelial membrane antigen (EMA), vimentin, CD10 (focally), and CK7 (focally)." (PMID 23533895, 2013). "All antigens, and particularly EZR, VCL, VIM, PDC6I, hnRNPL and ANXA2 induced a specific antibody response in KC and KPC already at 1 to 3 months of age, when the tumor stage was limited to early PanIN." (PMID 24010981, 2013). "Vimentin is required to maintain the architecture of the cytoplasm, and aberrant vimentin expression during EMT is suggested to be an essential element for epithelial plasticity and tumor cell metastasis." (PMID 23717685, 2013). "Immunohistochemically, the tumor cells expressed usual vascular antigens CD31 and CD34 as well as mesenchymal marker, Vimentin." (PMID 22280556, 2012). "The intermediate filament vimentin is an important marker of EMT and its expression is related to the adhesion and migration properties of tumor cells." (PMID 23216791, 2012). "Vimentin, in particular, was immunolocalized in the cytoplasm of OSCC cells at the invasive tumor fronts." (PMID 22548191, 2012). "Immunohistochemistry showed the tumor cells were diffuse (over 50% of tumor cells) positive for pan-CK, p63 and Vimentin, CD31 was also strongly expressed in tumor cells." (PMID 22943673, 2012). "Treatment with SD208 (2 μM) for 14 days strongly reversed the tumor exosomes-induced expression of CAF markers including FAP, α-SMA, N-cadherin and Vimentin in hucMSCs." (PMID 23285052, 2012). "Compared to the untreated group, tumor exosomes treatment resulted in increases in FAP, α-SMA, N-cadherin, and Vimentin protein levels." (PMID 23285052, 2012). "The tumor cells showed strong, diffuse positive cytoplasmic staining to HMB45, S100, vimentin and strong nuclear reactivity to microphthalmia transcription factor (Mitf)." (PMID 22957287, 2012). "Microscopically, the inner components of the tumor consisted of variously sized vascular spaces lined by a single layer of flattened cells, which stained positive with CD34 and vimentin." (PMID 23216883, 2012). "The tumor showed diffusely positive reactivity with cytokeratin (Pan), cytokeratin 19, cytokeratin 5/6, cytokeratin 7, EMA, vimentin, CD56, and NSE and also showed variable reactivity with glial fibrillary acidic protein (GFAP) and VEGF." (PMID 22472343, 2012). "For each tumor line, both SC5 and V9 mAbs specific for vimentin were capable of detecting surface expression representing two different regions of the protein." (PMID 24212937, 2011).
tumor (continued). "After exposure to the tumor microenvironment, MSCs acquire expression of TAF antigens, such as α-smooth muscle actin, fibroblast-specific protein, vimentin, and SDF-1 in vivo and in vitro following coculture with tumor cells or using tumor-conditioned media." (PMID 21280155, 2011). "As a population, Vimentin+CD44+CD133+ cells represented approximately only 0.3, 0.4 and 5% of the total sorted tumor cell population for the DU145, PC3 and LNCaP lines, respectively." (PMID 24212937, 2011). "In vivo, depletion of PMN-MDSC reduced the density of vimentin and S100A4 expressing cells in the primary tumor." (PMID 21980263, 2011). "In summary, given the facts that the expression of CD44 and vimentin correlate with EMT in cancer cells, and with tumor angiogenesis, our findings provide rationale for further functional studies on the role of these proteins in EMT and angiogenesis." (PMID 22216242, 2011). "The expression of VIM and TWIST1 increased according to tumor dedifferentiation and was highest in SCK cells (left)." (PMID 21333016, 2011). "The immunohistochemical analysis of the metastases revealed poorly differentiated high-grade tumor cells and strong OCT4 staining in most of the cells and weak positive staining for VIM, and this was similar to what was observed in primary tumors." (PMID 21952072, 2011). "The highest expression of SNAI2, TWIST1, VIM and lowest expression of CDH1 was found in the CCND1low/ID1high subgroup of tumours (yellow bars)." (PMID 21955753, 2011). "In contrast, in low-grade WAP-T tumors vimentin and SV40-LT expression is restricted to stromal and tumor epithelial compartments, respectively." (PMID 20730114, 2010). "Tumor cells demonstrated positive staining for the follicular dendritic cell markers CD21 (49/49), CD35 (43/45), CD23 (20/23), CD68 (23/25), Vimentin (22/28), and 18 cases showed immunostaining for S-100 protein." (PMID 20937101, 2010). "Immunohistochemically the tumour cells stained with calretinin, Cam5.2, CK7, vimentin and focally with EMA." (PMID 21151721, 2010). "We found down-regulation of E-cadherin and up-regulation of mesenchymal markers such as vimentin and ZEB1 in tumor tissues derived from PC3 PDGF-D cells compared with PC3 Neo control cells." (PMID 20805998, 2010). "Immunohistochemical stains performed on sections of the cell block demonstrated that the tumor cells were positive for vimentin, focally positive for smooth muscle actin, and positive for MIB-1 (Ki-67) in 20% of the tumor nuclei." (PMID 20436789, 2010). "In transplanted G-2 tumors and high-grade WAP-T tumors we observed in addition to the expected expression of vimentin in the stromal compartment also the co-expression of vimentin and SV40-LT in individual tumor cells." (PMID 20730114, 2010). "Co-staining for vimentin and SV40-LT (expression of SV40-LT is limited to tumor cells) allows to distinguish between stromal mesenchymal cells recruited into the tumors and tumor cells expressing a mesenchymal or an intermediate phenotype." (PMID 20730114, 2010). "On immunohistochemical staining, the tumor expressed focal smooth muscle actin (α-SMA) and vimentin, while a small number of tumor cells were also weakly positive to HHF-35, desmin and S-100 stains." (PMID 20205848, 2010). "Conversely, mesenchymal markers, such as vimentin (VIM), are induced in these cancer cells, all leading to a less adhesive, more motile cell morphology that allows local tumour cell evasion." (PMID 18334972, 2008). "On immunohistochemistry, tumor cells were positive for smooth muscle actin, keratin MNF 116 and vimentin." (PMID 17250774, 2007). "Immunohistochemically, the tumor cells are usually positive for S-100 protein, HMB-45 and vimentin and/or microphthalmia transcription factor." (PMID 16893467, 2006).
tumor (continued). "For example, bitransgenic MMTV-neu/MMTV-TGF-β1 mice exhibited higher levels of circulating tumor cells and lung metastasis than the MMTV-neu mice and the tumors from the bigenic mice had higher levels of vimentin as well as activated Smad2, Akt, and MAPK." (PMID 16457687, 2005). "These genes are mainly characteristic of previously defined 'stromal' signature, but that are produced by both tumor and stromal cells including collagens, TIMP2, bFGF, vimentin and SPARC." (PMID 16042759, 2005). "Immunohistochemically, all the tumours showed a constant expression of high molecular weight cytokeratins (Ck) Ck5 and Ck14, p63, SMA and vimentin." (PMID 16050957, 2005). "Immunohistochemical analysis of tumor tissues injected with 2B7 revealed decreased expression of the cancer stem cell (CSC) marker CD44, as well as changes in the epithelial-mesenchymal transition (EMT) markers E-cadherin and vimentin." (PMID 41356204, 2026). "Vimentin independently predicted disease-specific survival, while EMT-related alterations overall appeared strongly influenced by established clinicopathological factors, particularly tumor stage." (PMID 42278528, 2026). "Immunohistological classification of muscle-invasive bladder cancers revealed Cx32 expression to be informative in luminal tumour biology, with non-membrane localised Cx32 defining a Ki67-high, vimentin-expressing, and TGFβ-activated subset of luminal tumours." (PMID 41702673, 2026). "Furthermore, conditioned media (CM) from CIPp-EV–treated macrophages enhanced CIPp tumor cell migration and induced epithelial–mesenchymal transition (EMT), evidenced by the reduction of E-cadherin and increased expression of vimentin, fibronectin, and α-SMA." (PMID 41910820, 2026). "Tumor emboli were cytokeratin positive, supporting epithelial origin and an IMC diagnosis, and neoplastic cells were immunopositive for cytokeratin with concurrent vimentin immunoreactivity." (PMID 41828965, 2026). "In addition, Vimentin and PECAM1/CD31 were analyzed to further characterize the tumor microenvironment." (PMID 40694103, 2026). "Regarding Vimentin, biopsies were generally negative, with the exception of small tumor cell clusters (<5%) identified in G3 samples." (PMID 42294309, 2026). "The tumor cells were diffusely positive for α-inhibin, SF1, FOXL2, WT1, and Vimentin." (PMID 41584573, 2025). "In this study, we have observed that tumor organoids may maintain the key characteristics of the original TME, expressing α-SMA and vimentin in patterns similar to tumor tissue." (PMID 41035875, 2025). "Additionally, NT5E can reduce intercellular adhesion by regulating cadherin-1 and vimentin, thereby inducing epithelial-mesenchymal transition (EMT) and conferring an “invasive phenotype” to tumor cells." (PMID 40612859, 2025). "One was a nonepithelial tumor comprising immature spindle-shaped and stellate plaques, with positivity for the mesenchymal markers vimentin and CD68 and negativity for myogenic, neurogenic, and other markers." (PMID 40755904, 2025). "On IHC, tumour cells were positive for Vimentin, CD34 and S-100, while negative for STAT6, SMA and CK." (PMID 40556788, 2025). "The tumour cells were positive for Vimentin, CD34 and S-100 positive, while negative for SOX 10, EMA, SMA and Melan A. Ki 67 was approximately 11%." (PMID 40556788, 2025). "Moreover, mIF analysis of subcutaneous tumor xenografts in BALB/c nude mice revealed increased staining of p16 and vimentin in the IR group, which was reversed with IR+anakinra treatment." (PMID 39903771, 2025).
tumor (continued). "In particular, tumor cells located in the tumor periphery showed strong vimentin positivity in controls, whereas ADAMTS13‐deficient tumors showed almost no vimentin staining." (PMID 41211185, 2025). "Immunohistochemical examination showed that tumor cells were strongly positive for vimentin, SMA, and P16 but negative for desmin, CK, P40, P63, CK5, HMB45, MyoD1, myogenin, S100, and SOX10." (PMID 39872225, 2025). "Furthermore, Dox-loaded AS-T9/U4_MH effectively downregulated hTERT and vimentin expression in SW480 cells, indicating its potential in inhibiting epithelial-mesenchymal transition (EMT) and tumor progression." (PMID 39946362, 2025). "APOL1, TNF, and VIM co-expressed in myeloid cells, indicating that PANoptosis–lactylation interplay may counteract APOL1’s tumor-promoting effects by activating caspase cascades." (PMID 40649778, 2025). "In addition, immunohistochemical analysis of tumor tissues showed that alpha-estradiol and (R)-(−)-ibuprofen inhibited the expression of GLI1, Zeb1 and Vimentin." (PMID 40255562, 2025). "Immunohistochemistry was significant for Ki-67 expression in 60% of tumor cells, positive staining for vimentin and P16, and negative staining for hepatocyte markers (arginase-1 and hepatocyte)." (PMID 40842593, 2025). "The first was a non-epithelial tumor consisting of immature spindle-shaped and stellate plaques that were positive for α-1 antitrypsin and the mesenchymal markers vimentin and CD68 but negative for myogenic, neurogenic, and other markers." (PMID 40755904, 2025). "In our case, the tumor exhibited positive staining for CK5/6, P40, P63, and CK7, while showing negative staining for Napsin A, TTF-1, CD56, Chromogranin A, Synaptophysin, Pax-8, thyroglobulin, and vimentin." (PMID 40061900, 2025). "Examination of the transplanted tumor tissues revealed that the group with MYBL2 overexpression exhibited marked activation of epithelial-mesenchymal transition (EMT), as evidenced by an upregulation of Vimentin and a downregulation of E-cadherin expression." (PMID 40092688, 2025). "Tumor cells were positive for α-inhibin, SF-1, FOXL2, WT-1, and Vimentin." (PMID 41584573, 2025). "Further immunohistochemistry study demonstrated that PLX3397 + TMZ combined therapy significantly decreased cell proliferation (Ki-67), invasion (Vimentin), angiogenesis (CD31), and increased apoptosis (cleaved caspase-3) in G422TN-tumor compared to their monotherapy or Ctrl groups." (PMID 41365876, 2025). "The presence of mesenchymal markers, such as vimentin (24.5% of patients) and N-cadherin (13.7% of patients) suggests that EMT plays a crucial role in the aggressive nature of this tumor subtype, potentially contributing to poorer prognosis and increased metastatic potential." (PMID 39858010, 2025). "When tumor diameter and vimentin(+), CD10(+), CD34(+), and c-Kit(+) telocyte cell numbers were compared, c-Kit(+) (p = 0.032) telocytes were less numerous in patients with a tumor diameter larger than 5 cm than in patients with a tumor diameter of 2–5 cm." (PMID 40724542, 2025). "Positive staining of PD-L1, CD31 (partial +), CD34, CD68, CD163, vimentin and SMA detected in the tumor tissue, indicating that vascular endothelial cells, TAMs and fibroblasts may participate in the pathogenesis of ENKTL." (PMID 40433378, 2025). "Tumour cells showed cytoplasmic expression of vimentin and α-SMA and were negative to desmin, S-100 and c-Kit." (PMID 40045318, 2025). "In triple‐negative breast cancer (TNBC), vimentin R64 aDMA levels correlate with advanced tumor stage and poor patient survival." (PMID 40884268, 2025). "This accumulating evidence supports the notion that vimentin is not just a biomarker of EMT but a functional driver that regulates tumor invasion, fibrosis, organ development, and cellular plasticity across multiple biological contexts." (PMID 40618999, 2025).
tumor (continued). "Concurrently, RT-qPCR analysis revealed that the expression levels of tumor proliferation markers (MCM2 and Ki-67) and epithelial-mesenchymal transition (EMT)-related markers (CDH2, VIM, and FN1) were also significantly elevated following TRPM6 knockdown, consistent with the phenotype assay results." (PMID 41562086, 2025). "Progesterone correlated with EMT protein expression in healthy mucosa (e.g., fibronectin in females: ρ = 0.567, p = 0.014; vimentin in males: ρ = −0.446, p = 0.007), but not in tumor tissue." (PMID 40507970, 2025). "In this study, Vimentin serves as an important bridge between KLF5 and tumor cell stemness." (PMID 40307891, 2025). "The tumor cells consistently express S100 protein and vimentin and are negative for CD1a, Langerin (CD 207), CD21, CD23 and CD35." (PMID 40088330, 2025). "In addition, it is well established that vimentin plays a crucial role in regulating EMT, a pivotal process in tumor progression." (PMID 40083939, 2025). "The tumor cells of IS and AS were diffusely positive for Vimentin (11/11, 100%) but negative for CKpan." (PMID 41246336, 2025). "Our findings suggest that CLCA4 could impede colorectal CSC self-renewal by interacting with vimentin to suppress the FAK signaling pathway, potentially reducing tumor cell stemness and evading immune surveillance." (PMID 41674659, 2025). "Circulating tumor cells can undergo epithelial‐mesenchymal transition (EMT) thereby reducing the expression of epithelial markers such as EpCAM and CK8/18/19 and increasing the expression of mesenchymal markers such as vimentin (Vim) and c‐MET." (PMID 38956984, 2025). "Immunohistochemistry showed weak GFAP and vimentin expression, and the tumour was negative for cytokeratin (AE1/AE3), S100 and EMA." (PMID 41033792, 2025). "Different from LNCaP95 metastatic tumor cells, vimentin was primarily expressed in the cytosol of metastatic PC‐3 tumor cells, and its expression decreased following treatment with SCORT‐CasRx‐pre‐gHoxB13, suggesting a decrease in tumor growth and metastasis." (PMID 40349174, 2025). "Specifically, in FOXL2+COL1A1− cells, we examined expression of other AGCT tumor markers such as SF1, calretinin, and inhibinα, whereas in FOXL2+COL1A1+ cells, we also examined expression of stromal markers, including αSMA, vimentin, S100A4, PDGFRa, PDGFRb, and FAP." (PMID 41042551, 2025). "In a lung multicellular tumor spheroid (MTS) model, the GSK-3β inhibitor CHIR-99021 significantly increases the expression of CD31 and VE-cadherin, while inhibiting the expression of α-SMA and vimentin in HUVEC cells." (PMID 40650130, 2025). "However, our sample varied when comparing the staining of Vimentin (+) and AMACR (-) to the tumor samples found within the Al-Obaidy study." (PMID 40989704, 2025). "Immunohistochemistry showed that tumor cells were CAM5.2 (+), AE1/3 (+), Ber-EP4 (–), EMA (+), CD45 (+), NSE (+), Synaptophysin (–), Chromogranin A (–), CD56 (+), NKX2.2 (–), Vimentin (+), GFAP (–), S-100 (–), Desmin (–), SMA (–), WT1 (–), MyoD1 (–), Myogenin (–)." (PMID 40034204, 2025). "Thus, NORAD knockdown in HNSCC-derived tumor stem cells attenuates migration and invasion, lowers the expression levels of EMT-related markers, like MMP2, MMP9, N-cadherin, and vimentin, and upregulates E-cadherin expression." (PMID 41020820, 2025). "Immunohistochemistry showed that the tumor cells positively expressed CD99 and vimentin, some cases could positively expressed NSE, but negatively expressed S100, neurofilament protein, desmin and keratin." (PMID 41267976, 2025). "Mechanistically, these observations align with bioinformatic analyses highlighting PDGFRβ as an upstream regulator of multiple downstream effectors—PPARγ, VEGFA, ANG-2, VIM, COL1A1, and Cadherins all integral to tumor progression, angiogenesis, and cellular plasticity." (PMID 40282535, 2025).